LINC01096 (long independently transcribed non-coding RNA 1096)
Gene: Long non-coding RNA gene on chromosome 4 (13,546,075 to 13,547,822, reverse strand). Ensembl gene ENSG00000246095.
Diseases named in the same sentence as LINC01096 in open-access papers:
LINC01096 is named in the same sentence as 1 disease in open-access papers, as found by Europe PMC text mining. Sharing a sentence is not in itself a finding about the gene and the disease.
LINC01096 shares sentences with these, for which no sentence is quoted: breast carcinoma (1 paper).